CD44 (CD44 molecule (IN blood group))
Diseases named in the same sentence as CD44 in open-access papers (continued):
Sharing a sentence is not in itself a finding about the gene and the disease.
liver cancer (continued). "Interestingly, in the liver cancer cell line HepG2, shRNA-based TRPV2 knockdown promoted the expression of stem cell markers (i.e., CD133, CD44, and ALDH1), spheroid, and colony formation." (PMID 33376561, 2020). "Liver cancer cells with stem cell phenotypes generally highly express well-known stem cell-related molecular markers, such as Oct-4, Sox-2, Nanog, Epithelial cell adhesion molecule (EpCAM), CD90, CD133, and CD44." (PMID 31185668, 2019). "Interestingly, CD44 regulates the survival and the tumorigenic activity of CD90+ liver cancer cells." (PMID 28930164, 2017). "Moreover, the up-regulation of some genes related to the stemness of cancer cells, such as EpCAM, CD133, CD44, Oct4, Nanog, KLF4 and Sox4, in USP16-depleted liver cancer cells also suggests a stemness-suppressing role for USP16." (PMID 27633997, 2016). "Moreover, prolonged MB109 treatment suppressed the expression of five prominent liver cancer stem cell (LCSC) markers, including CD44, CD90, AFP, GPC3 and ANPEP." (PMID 27650540, 2016). "Moreover, PTEN/Akt signaling is also involved in CD44+/CD133+ CSCs in other solid tumors, not only in liver cancer." (PMID 24721996, 2014). "Additionally, to investigate the correlations between SERPINB2 and CSC populations in various cancer patients, we analyzed the co-expression of SERPINB2 in CD44-, CD133- or ALDH-positive tissue samples from breast, colorectal and liver cancer patients, respectively." (PMID 30965654, 2019). "Likewise, CD44 expression levels, migration, and invasiveness but not cell activity of liver cancer cells was affected." (PMID 31294922, 2019). "By taking these factors together, we concluded that our simple and cancer-favoring strategic virus design of the CVV eradicates metastatic CD44-expressing cells, provided that our CVV may be a promising therapeutic reagent that targets metastatic liver cancer cells." (PMID 29069721, 2017). "Interestingly, CD44 and ALDH1 were also highly expressed in CTCs from the liver patient, suggesting that these two markers may be also conserved in CTCs in liver cancer." (PMID 29062075, 2017). "Western blotting showed that liver cancer stem cells CD133, CD44, CD24 and EpCAM were expressed in human liver cancer stem cells(HLCSC), as well as CD133, CD44, CD24 and EpCAM were not expressed in liver cancer unstem cells (non-HLCSC)." (PMID 26513297, 2015). "Additionally, we demonstrated the meaningful relationship between the CD44 and DSS of liver cancer patients, unlike the public DB." (PMID 34208132, 2021).
leukemia (109 papers, 2008 to 2025). A malignant (clonal) hematologic disorder, involving hematopoietic stem cells and characterized by the presence of primitive or atypical myeloid or lymphoid cells in the bone marrow and the blood. "CD44 is a ubiquitous cell surface glycoprotein implicated in solid cancer and leukemia migration/adhesion." (PMID 39580584, 2025). "The presence of various complex patterns of CD44 variant exons, particularly exon v6, has been observed in the majority of leukemia samples." (PMID 38736891, 2024). "E-selectins on the BM endothelium support homing of CML LSC via CD44 and lead to decreased proliferation of leukemia cells and reduced susceptibility to TKI treatment." (PMID 36163264, 2022). "The binding of HA to CD44 triggers the signaling of RhoA through the leukemia-associated Rho guanine nucleotide exchange factor (LARG)." (PMID 30676222, 2019). "In many other cancer types and leukemias, CD44 has gained clinical interest because CD44s and variant isoforms (CD44v) feature “stemness” potential." (PMID 28163708, 2017). "The CD44-EGFR complex also associates with leukemia-associated Rho-guanine (LARG) nucleotide exchange factor activating downstream signaling through ras and RhoA." (PMID 23855374, 2013). "Here, we identify cFos as a critical cAMP effector, able to regulate the re-expression and splicing of epigenetically silenced genes associated with maturation (CD44) in retinoid-resistant NB4-LR1 leukemia cells." (PMID 23209736, 2012). "In addition, leukemia-associated immunophenotype pattern (LAIP) markers CD44 6 (86%) and CD123 5 (55%) were also found to be significantly associated with Ph+ve, whereas their values in the Ph-ve group were lesser at 25 (42%) and 9 (17%), respectively." (PMID 39371707, 2024). "Mass cytometry further revealed that YW3-56 treatment simultaneously suppresses leukemia stemness (CD44/CD133 downregulation) and promotes myeloid differentiation (CD11b/CD14 upregulation), as well as enhances immunogenic activation (CD80/CD86 increase)." (PMID 41304891, 2025). "In leukemia, CD44 downregulation reduces β-catenin levels, inducing cell cycle arrest and inhibiting proliferation." (PMID 40363706, 2025). "From a more in-depth analysis of the distribution/expression pattern of the single proteoglycans, CD44 appears to be most ubiquitous proteoglycan across hematologic neoplasia, being also abundant on leukemia-initiating stem cells." (PMID 39980017, 2025). "In such experimental paradigms of myeloid leukemiagenesis, CD44 seems capable of purporting the activity of leukemia-initiating cells following their sequential transplantations into diverse hosts." (PMID 39980017, 2025). "Seven leukemia-associated immunophenotype pattern (LAIP) markers, CD9, CD44, CD58, CD73, CD81, CD86, and CD123, were also included in the diagnostic panel." (PMID 39371707, 2024). "In this review, we focus on the impact of CD44s/CD44v as biomarkers in leukemia development and discuss the current research and prospects for CD44-related interventions in clinical application." (PMID 38736891, 2024). "The outer layer that targets both CD20 and CD44 ensures accurate attachment to leukemia cells, effectively triggering leukemia cell apoptosis and inhibiting their proliferation." (PMID 39128942, 2024). "In the field of leukemia treatment, CD44 can also be applied for universal minimal residual disease (MRD) monitoring, as its high expression levels are always associated with poor prognosis." (PMID 38736891, 2024). "As an important prognostic indicator, the upregulation of CD44 exhibits statistically significant implications in the cell fate of many cancer cells, including leukemia cells." (PMID 38736891, 2024). "Hyaluronic acid is a classic ligand of CD44, and studies have shown that the content of HA in the bone marrow of leukemia patients is significantly increased." (PMID 38971796, 2024).
leukemia (continued). "The prognosis is inversely correlated with the expression levels of CD44 in leukemia cells and their rate of increase; however, further evidence is needed to fully support the underlying mechanism." (PMID 38736891, 2024). "Although the mechanism of action regarding CD44 exosomes on leukemia cells still needs further research, it undoubtedly provides a new approach for targeting CD44 on leukemia." (PMID 38736891, 2024). "It has been discovered that CD44 promotes the proliferation of leukemia cells through upregulating expression of anti-apoptotic protein myeloid cell leukaemia-1 (MCL-1)." (PMID 38736891, 2024). "Concordantly, we verified that the content of HA in the bone marrow of leukemia-bearing mice was significantly higher than that of normal mice, confirming that CD44-HA axis is involved in mediating bone marrow targeting of HSPC-Lipo." (PMID 38971796, 2024). "Due to its widespread presence and varying expression levels at each stage of leukemia development and across diverse subtypes of leukemia, CD44 has been considered as a valuable biomarker." (PMID 38736891, 2024). "For example, it was shown that the miR-29b/Sp1/FUT4 axis promotes the malignant behavior of leukemia stem cells by regulating CD44 through the Wnt/β-catenin pathway." (PMID 39056681, 2024). "Targeting Wnt signaling in leukemia represents an attractive therapeutic strategy to suppress the leukemia-initiating properties of the CD44+CD133+ cells." (PMID 37568748, 2023). "HA not only has an excellent biodegradability but also has high selective binding to CD44, which was increased in various cancer cells, including breast cancer, liver cancer, osteosarcoma and leukemia." (PMID 36110161, 2022). "Our ex vivo experiments revealed that the level of cell-surface glycoprotein CD44 decreased in Tregs as a result of leukemia progression." (PMID 35296093, 2022). "Expression of the leukemic stem cell antigen CD44 was increased in EVs from both leukemia types, AML and B-ALL, compared to EVs from HBDs." (PMID 35008226, 2021). "Our results showed that ampelopsin suppresses the expression of leukemia stemness markers, including Oct4, Sox2, CD44, and CD133, in HL60 and K562 cells." (PMID 33924032, 2021). "In acute myeloid leukaemia cells, the binding of CD44 and HA enhanced cell proliferation, and blocking this binding significantly inhibited the growth of CD44+ leukaemia cells." (PMID 34944493, 2021). "Especially in leukemia, CD44 has been utilized among others to specifically target leukemia stem cells in human AML." (PMID 34307351, 2021). "As predicted, at this early time point, TCR2C had already begun to expand and upregulate CD44 expression almost exclusively in the spleens of leukemia-challenged animals." (PMID 34758311, 2021). "MLL-R ALL had a unique genetic profile clearly distinguishable from those of other types of leukemia, with very high CD44 levels." (PMID 31523525, 2019). "It was recently reported that the binding of the inflammatory mediator ultra-low-molecular-weight hyaluronan (ULMW-HA) to CD44 in B-precursors leukemia cells resulted in necrosis." (PMID 29534721, 2018). "CD44 is a glycoprotein expressed in leucocytes and a marker of leukemia-initiating cells, being shown to be important in the pathogenesis of T cell acute lymphoblastic leukemia (T-ALL)." (PMID 30430079, 2018). "Among them, CD44 stood out, since it has been found elevated in several kinds of leukemias, including CML26, and plays crucial roles in leukemia stem cell maintenance and self-renewal." (PMID 30154435, 2018). "As it relates to leukemia, CD44 expression promoted both CML and AML stem cell maintenance in mouse models." (PMID 30154435, 2018). "First, because microarray analysis showed elevated CD44 expression following AF1q upregulation and, second, because CD44 was demonstrated to be crucial for leukemia stem cell maintenance and self-renewal." (PMID 30154435, 2018).
leukemia (continued). "The categories overlap: for example, amongst the adhesion related genes, ITGB3 and CD44 are also essential for the maintenance of leukaemia initiating cells." (PMID 29340063, 2017). "Currently, multiple anti-CD44-based therapeutic approaches are investigated for their ability to target leukemia- or cancer-initiating cells (LIC/CIC) with this “stemness” potential." (PMID 28163708, 2017). "ULMW-HA-triggered cell death was similarly demonstrated in surface CD44-high primary B-precursor leukemia cells." (PMID 28569787, 2017). "Such agents should be very effective by predominantly eradicating CD44-positive leukemia- or cancer-initiating cells." (PMID 28569787, 2017). "CD97 knockdown also decreased the levels of CD44, which is expressed in several leukemia and carcinoma cell types and is a marker of cancer-initiating cells." (PMID 26233326, 2016). "Studies in a murine model confirmed leukemia cell homing and growth retardation by a CD44-specific antibody." (PMID 26074915, 2015). "In view of the most promising results in leukemia therapy by blocking CD44, awareness increased on possible selective differences between HSC and LIC in the crosstalk with the osteogenic niche." (PMID 26074915, 2015). "Last, the interplay between CD44 and HA accounts for rapid drug elimination via drug transporters, which creates a major obstacle in leukemia and cancer therapy." (PMID 26074915, 2015). "The antibody decreased proliferation of the primary T-ALL cells and depleted leukemia initiating CD34/CD44 high population." (PMID 26046801, 2015). "A blockade of CD44 is considered a therapeutic option for the elimination of leukemia initiating cells." (PMID 24684724, 2014). "CD44 also is frequently overexpressed in leukemia such that LIC can be driven into differentiation and death by anti-CD44." (PMID 24684724, 2014). "High CD44 expression in many leukemia and lymphoma has stimulated therapeutic considerations based on a blockade of CD44 that was particularly successful in AML and CML." (PMID 24684724, 2014). "CD44, in particular, is believed to prevent homing of leukemia stem cells to the bone marrow, thus representing an attractive target for AML therapy." (PMID 24504051, 2014). "Herein we show that in leukemia cells ERG overexpression promotes a mesenchymal-like gene expression signature that includes: CD24, CD44, ITGA10, ITGB5, ITGB3, ITGA2B and the morphogenic-associated genes, such as SHANK3, TYROBP." (PMID 24504051, 2014). "Our studies, confirming that leukemia cell homing and growth is retarded by a CD44-specific antibody, pointed towards an antibody blockade of CD44 during reconstitution to affect HSC embedding more severely than leukemia growth." (PMID 24684724, 2014). "Firstly, we showed that CD44 expression was increased in several kinds of leukemia patients and K562 cells." (PMID 24257075, 2013). "The real-time PCR analysis revealed that the expressions of CD44 in leukemia patients were higher than that in healthy subjects, although the degrees of discrepancy were different." (PMID 24257075, 2013). "Then we respectively chose one patient from each kind of diseases to compare the protein expression of CD44 between leukemia patients and healthy volunteers." (PMID 24257075, 2013). "The expressions of CD44 in different leukemia patients and cell lines were detected by real-time PCR and western blotting." (PMID 24257075, 2013). "More selective antigens for the AML leukaemia stem cell are under investigation (such as CD123 or CD44), in case of limiting myeloid toxicity related to the CD33 targeting." (PMID 22272203, 2012). "While a relatively constant amount of HA is in circulation, these HA polymers indeed regulate the physiological function of normal blood leukocytes, leukemia and cancerous cells via membrane CD44 and other receptors." (PMID 19484134, 2009).
leukemia (continued). "CD44 is involved in the development and progression of hematological malignancies by enhancing apoptotic resistance and invasiveness, as well as regulating bone marrow homing and mobilization of leukemia-initiating cells into the peripheral blood." (PMID 39851489, 2025). "Consequently, it can be inferred that CD44 exerts regulatory control over leukemia cells through the Wnt/β-catenin pathway." (PMID 38736891, 2024). "Moreover, as a key coordinator of the interaction between leukemia cells and the bone marrow microenvironment, CD44 plays an important role in mediating cellular homing." (PMID 38736891, 2024). "The expression of CD44 subtypes and their clinical significance in leukemia." (PMID 38736891, 2024). "Moreover, wrapping PTL with PLGA and an anti-CD44 target antibody was an effective measure to promote uptake by leukemia cells." (PMID 37491290, 2023). "For example, wrapping PTL nanoparticles with PLGA and anti-CD44 could enhance their bioavailability to leukemia cells." (PMID 37491290, 2023). "The mAbs against CD44 have been considered a therapeutic option for solid tumors and leukemia." (PMID 37504249, 2023). "In conclusion, the bone and CD44 dual targeting liposomes with redox sensitivity could target to the leukemia stem cells regions and then uptake by the tumor cells, which would be a valuable target for the treatment of the AML." (PMID 36110161, 2022). "Taken together, in vivo experiments indicated that the redox sensitivity liposomes with bone and CD44 dual targeting enabled a specific and efficient delivery of the AraC to the leukemia cells, which could kill the leukemia cells in mice." (PMID 36110161, 2022). "Moreover, ampelopsin suppressed the expression levels of leukemia stemness markers, such as Oct4, Sox2, CD44, and CD133." (PMID 33924032, 2021). "In addition, we confirm that CD44, which is crucial for leukemia stem cell homing, survival, and proliferation, is regulated by AF1q." (PMID 30154435, 2018). "Further, the CD44-targeting may become an effective approach in future for the treatment of refractory B-precursor ALL by its capability of predominantly eradicating CD44-high leukemia-initiating cells." (PMID 28569787, 2017). "Deregulated CD44 contributes to leukemogenesis, and blocking CD44-mediated adhesion by complexing antibodies to aid in the detachment of leukemia cells from the bone marrow niche has been proposed as a targeted therapy in leukemia." (PMID 24504051, 2014). "In addition, Kasumi-1 exosomes also carried proteins known to be expressed in leukemia stem cells: CD44, CD200 and CD105." (PMID 25093329, 2014). "A blockade of CD44 retards homing and leukemia growth in BM and spleen." (PMID 24684724, 2014). "But in leukemia genesis the relationship between CD44 and β-catenin was little studied." (PMID 24257075, 2013). "We first compared CD44 expression of patients with different leukemias by PCR and real-time PCR." (PMID 24257075, 2013). "Furthermore, high level expression of CD44 by leukemia cells was sufficient to generate leukemia by leukemia-initiating cells even after withdrawal of overexpression of the HoxA10 gene that initiated the leukemia." (PMID 22346731, 2012). "Cytokine/RAS-induced CD44 upregulation, or de novo transcription of the proteoglycan is not exclusive of B-ALL, but is also characteristic of T-ALL, AML, myelodysplastic erythropoiesis, CLL-B and more infrequent leukemia variants, such as erythroleukemia and mast cell leukemia." (PMID 39980017, 2025). "CD44 mediates cell–cell or cell–extracellular matrix interactions, and its blockade with a monoclonal antibody had been shown to revert differentiation block of myeloblasts, inhibit their proliferation, and block leukemia stem cells (LSC) from trafficking to their supportive niche." (PMID 32134197, 2020).